RXRG (retinoid X receptor gamma)
Diseases named in the same sentence as RXRG in open-access papers (continued):
Sharing a sentence is not in itself a finding about the gene and the disease.
tumor (continued). "In ER-positive tumours, high expression of RXRG was associated with better patient outcome regardless of adjuvant systemic therapy." (PMID 31558802, 2019). "RXRG positivity was associated with a significant survival advantage in patients with ER-positive tumours irrespective of hormonal therapy (p = 0.049 and p < 0.0001, respectively)." (PMID 31558802, 2019). "Multivariate analysis incorporating these variables confirmed RXRG expression as an independent predictor of LNM (OR 1.598, 95% CI 1.043–2.448; P = 0.031), along with tumor stage." (PMID 40465540, 2025). "It was notable that retinoic acid (RA) signalling TFs, including RA nuclear receptors RXRA, RXRG, and RXR-interacting partner ZNF42356, all had increased activity in these residual tumour cells." (PMID 39341888, 2024). "ScATAC analysis identified enrichment of TF motifs for hepatic development in the fetal-I and II tumor organoids, such as HNF family members (HNF4A, 4 G, 1B, 1 A), RXRG and PPARD." (PMID 39567475, 2024). "In tumor specimens from the lung, the mRNA levels of RXR genes RXRα and RXRγ were shown to be considerably lower." (PMID 35631448, 2022). "Retinoid X Receptor Gamma (RXRG) is a member of the nuclear receptor superfamily and plays a role in tumour suppression." (PMID 31558802, 2019). "Retinal organoids staining positively with the RXRG cone marker (day 65–70) were incubated with vehicle, sunitinib, topotecan, or melphalan [at the IC50 for tumor organoids for 24 h], and cell death was examined by immunostaining of cleaved caspase 3 (CC3), a marker of apoptosis." (PMID 36726110, 2023). "The results of DNA samples from 40 cancer and 25 normal lung tissues showed a good diagnostic potential of selected RCGY sites in regulatory regions of MYF6, SIX6, RXRG, LHX1, RASSF1A and TERT genes with relatively high sensitivity (80.0 %) and specificity (88.0 %) of LC detection in tumor DNA." (PMID 31526458, 2019). "Furthermore, five of the top ten NR genes that were shown to differ significantly between tumor and normal tissue were common to both datasets (i.e., AR, MR, NGFIB3, PPARγ, and RXRγ)." (PMID 21179495, 2010). "The NGFR and RXRG genes were upregulated in all non-MEL, non-MES samples, suggesting their stem-like characteristics, while they were found with low expression levels in MES- and MEL-like tumours, as expected." (PMID 36765773, 2023). "There was a slight increase in the number of non-cycling cells (RXRG+) after treatment of RB170 with the tested drugs, but only sunitinib significantly decreased the number of cycling cells (RXRG+ Ki67+), resulting in a reduced proportion of proliferative tumor cones." (PMID 36726110, 2023).
cancer (17 papers, 2013 to 2025). A tumor composed of atypical neoplastic, often pleomorphic cells that invade other tissues. "i.e., ACACB and RXRG were with high mutation frequency and down-expressed in most cancer types, including UCEC, LUAD, LUSC, COAD, BLCA and HNSC." (PMID 31074374, 2019). "To examine this in our cancer models, we compared the expression of RARα, RARβ, RARγ, RXRα, RXRβ and RXRγ in AB1-HA tumors, which are sensitive to combination tretinoin–CY therapy, and AE17, CT26 and WEHI164 tumors, which are resistant." (PMID 38350880, 2024). "We were shocked to learn that all three immunologic activation genes (CXCL10, RXRG, and SCG2) have been linked to cancer progression." (PMID 36685954, 2022). "On the other hand, Retinoid X receptor RXRG which is a regulator of 15 high centrality differentially regulated genes is downregulated in 12 cancer types." (PMID 34728699, 2021). "In contrast, low RXRG immunopositivity was observed in the nuclei of invasive cancer cells, with some malignant cells additionally featuring cytoplasmic staining." (PMID 31558802, 2019). "Previously published work from our group noted that RXRg expression is very high in CM cell lines while essentially unexpressed in every other tissue type in the NCI-60 cancer cell line panel." (PMID 26217306, 2015). "RXRG was found to have positive correlation with better cancer prognostic." (PMID 34805166, 2021).
infection (3 papers, 2009 to 2024). The state of being infected such as from the introduction of a foreign agent such as serum, vaccine, antigenic substance or organism. "shRXRγ infection appears to have partially decreased RXRα protein expression as well (likely via an indirect mechanism since shRXRγ are highly specific for RXRγ) which may contribute to the diminished LGD1069 effect." (PMID 19267912, 2009). "It appears as if the presence of S100A2 is important for optimal RXRγ expression, but this is most likely not a direct interaction as measurable and at least partially functional RXRγ (as evidenced by response to LGD1069) was seen after shS100A2 infection." (PMID 19859558, 2010).
metabolic disease (1 paper, 2025). A congenital disorder (due to inherited enzyme abnormality) or acquired (due to failure of a metabolically important organ) disorder resulting from an abnormal metabolic process. "This discovery offers new insights into PPARγ biology and its regulation, and suggests that RXRγ could be a valuable target for addressing metabolic diseases." (PMID 40855678, 2025).
nervous system disease (1 paper, 2021). "In the present study, we found that some genes of benefit to nervous system disease were activated (such as Lhx8, GPR88, RGS9, CD4, DRD2, RXRG, and Syt6), following the increase in the number of cholinergic and GABAergic neurons in the HSHF-diet offspring." (PMID 33819195, 2021). "As the offspring became older (16 months of age), we found that some genes of benefit to nervous system disease were activated, such as Lhx8, GPR88, RGS9, CD4, DRD2, RXRG, and Syt6, following the increase in the number of cholinergic and GABAergic neurons." (PMID 33819195, 2021). "When the offspring grew older (16 months), we found that some genes of benefit against nervous system disease were activated, such as Lhx8, GPR88, RGS9, CD4, DRD2, RXRG, and Syt6, and the expression of cholinergic and GABAergic neurons biomarker protein increased." (PMID 33819195, 2021).
RXRG also shares sentences with these, for which no sentence is quoted: epithelial ovarian cancer (2 papers); ovarian cancer (2); age (1); allergic rhinitis (1); asthma (1); Brain diseases (1); cannabis dependence (1); cardiomyopathy (1); colorectal cancer (1); diabetic retinopathy (1); ductal carcinomas in situ (1); gestational diabetes mellitus (1); glioma (1); glycogenosis (1); Hypocalcemia (1); Insulin resistance (1); invasive ductal breast carcinoma (1); invasive lobular carcinoma (1); Kaposi's sarcoma (1); myopathy (1); neuroblastoma (1); Parkinson’s (1); prostate carcinoma (1); psychosis (1); teratocarcinoma (1); virus infections (1).